IL1B (interleukin 1 beta)
Diseases named in the same sentence as IL1B in open-access papers (continued):
Sharing a sentence is not in itself a finding about the gene and the disease.
tumor (continued). "Our observations suggested a possible subgrouping of CRC on the basis of stromal, or tumor-derived PTGS2, the former modulated by IL1β, with a prognostic significance, the latter relatively independent." (PMID 32168749, 2020). "The BCL2, IL1-β, GFAP and KI67 levels in C6 tumor cells exposed with Ator and MSCs significantly activated compared to control sample." (PMID 32981013, 2020). "We next investigated if tumor-secreted BMP7 regulates IL1A, IL1B, TNF, and CCL5 via MAPK14 in macrophages." (PMID 32973129, 2020). "Elevated levels of IL-1β were observed in many different GBM cell lines and in human GBM tumor specimens." (PMID 32973662, 2020). "The main mechanism by which CAFs promote the progression of CCA is to support the proliferation and survival of tumor cells through the expression of cytokines and growth factors, such as periostin, thrombospondin-1, SDF-1, MMP2, MMP9, and IL-1β." (PMID 32539768, 2020). "M1 macrophages are conventionally activated macrophages that secrete pro-inflammatory cytokines such as IL-1β, IL-6, IL-8, IL-18, TNF-α, and IFN-γ, and exert an anti-tumor effect." (PMID 32993787, 2020). "Interestingly, our recent study demonstrated that IL-1β was required for the upregulation of PD-L1 expression by viral lytic reactivation from KSHV-infected tumor cells, which may represent a novel mechanism for virus-associated tumor cell immune escape." (PMID 33194830, 2020). "Consistent with the disruption of the BSCB, remarkably increased levels of IL-1β, TNF-α and MMP9 were observed in the tumor group of mice." (PMID 32796132, 2020). "In this study, immunohistochemical expression of TNF-α, IL-6, IL-1β, and IL-2 in GEP-NENs was evaluated and correlated with the proliferation, tumor grade, tumor, node, metastasis (TNM), and outcomes." (PMID 32156252, 2020). "Such cytokines IL-8, IL-6, IL-1β, TNF-α, IL-10, and others can be up-regulated and consequently contribute to tumor progression." (PMID 32277014, 2020). "Similar increases in phagocytosis and IL-1β secretion were also observed in macrophages purified from tumor tissues and co-cultured with PTX-treated tumor cells." (PMID 32724476, 2020). "In contrast, NaHS did not promote or only modestly promoted the synthesis of molecules that are frequently up-regulated under skin inflammatory conditions, namely VEGF and IL-1β." (PMID 32629886, 2020). "It is interesting to find that OSCC cells could secrete pro-inflammatory cytokines (such as IL-1β) and be influenced by microbiota or their cell components, which indicates a more complex interaction between cancer cells, immune cells and microbiota in tumour microenvironment." (PMID 32760436, 2020). "MDSCs and Treg cells increase the circulating levels of IL-1β, IFNγ, and CXCL10 that suppress the peripheral anti-tumor immune responses, and support CTC survival." (PMID 32260071, 2020). "Immunohistochemical analysis of tumor samples showed that the expressions of NLRP3 inflammasome and IL-1β were inhibited in MNS+CIK groups, furtherly indicating that MNS inhibits tumor growth through NLRP3 inflammasome inhibition." (PMID 32974137, 2020). "In addition, it was also reported that basophils could release pro-inflammatory cytokines such as TNF-α, IL-6 and IL-1β, which augmented the inflammatory anti-tumor reaction, resulting in direct anti-neoplastic functions and inducing the apoptosis of tumor cells." (PMID 32037496, 2020). "IL-1β-induced Tfh cells promote B cell maturation and class switch and stimulate effector CD8+ T cell responses against neo-antigens in the tumor microenvironment." (PMID 33584721, 2020). "By specifically targeting microglia, using propentofylline which blocks secretion of IL-1β, IL-6 and TNF-α, tumor growth was found to regress." (PMID 32765498, 2020). "Co-culture of BMDM with tumour cells led to increased expression of iNOS and CD206, and Il1α, Il1β, Il6 and Tgfβ in the BMDM." (PMID 32792542, 2020).
tumor (continued). "These iCAFs secrete a multitude of chemokines and cytokines (i.e., CXCL1, IL-1β, IL-6, OPN, etc.)that adds to the inflammatory milieu of the TME which further influences tumor growth, invasion, angiogenesis, metastasis, and immunosuppression." (PMID 32957515, 2020). "Pro-inflammatory cytokines such as IL-1β, IL-6 and TNF-α, secreted by microglia, have been shown to increase tumor invasiveness in vitro." (PMID 32765498, 2020). "The IL-1β-stimulated SCC7 and B16-F10 cells demonstrated stronger migration capability than the control tumor cells did." (PMID 32547321, 2020). "Tumor-induced factors, including prostaglandin E2 (PGE2), IL-6, IL-10, IL-1β, and transforming growth factor beta (TGF)-β have been shown to result in the recruitment and activation of MDSCs in the TME in malignant tumors." (PMID 33384962, 2020). "As hypoxia is an important event within the tumor, hypoxia-induced factor 1 (HIF1) was shown to regulate Il1b/IL1B transcription." (PMID 32635472, 2020). "We compared normal and tumor tissues for MK2 downstream cytokine production and also found a significant increase in IL-1β, IL-6, and TNF-α in tumors with lymph node metastasis compared to non-metastatic tumors." (PMID 32216812, 2020). "In a CAC model, oral pre-treatment with S. gallolyticus exacerbates both inflammation (e.g., IL-6, IL-1β, IL-8, CCL2, TNFα) and tumor formation." (PMID 32962159, 2020). "In supernatants from tumour cell killing assays, we found a similar immune mediator profile (TNFα, MCP-1, IL-10, CXCL-10, IL-1β, IL-6, and IL-23) to that previously detected with IgE cross-linking on the surface of monocytes." (PMID 33203088, 2020). "MDSC recruitment to the tumor can be induced by many different factors e.g. CSF3, IL-1β, and IL-6, and subsequently lead to activation of STAT3, rendering them potent as proangiogenic and immunosuppressive cells." (PMID 31690961, 2020). "In fact, IL-34 expressed by osteosarcoma cells, is regulated by IL-1β and TNF-α, can also recruit macrophages into tumor tissues." (PMID 33224886, 2020). "Tumor-induced EndMT is mediated by factors secreted from tumor cells, such as TGF-β2 and interleukin (IL)-1β." (PMID 32467609, 2020). "EBV latent membrane protein 1 (LMP1) was reported to increase the production of IL-1β, IL-6, and GM-CSF in NPC tumor cells, which finally promoted MDSC in the tumor microenvironment." (PMID 33290259, 2020). "In tumor cell lines where NLRP3 activation and, IL-1β and IL-18 secretion are low, Nigericin demonstrated an anti-tumor effect." (PMID 33613529, 2020). "TNFα, MCP-1 and IL-10, which we previously reported to be enhanced in the tumour microenvironment following systemic IgE treatment in vivo, were secreted by monocytes alongside immune mediators CXCL-10, IL-4, IL-1β and IL-23." (PMID 33203088, 2020). "Dying tumor cells release ATP, which activates the NLRP3 inflammasome in DCs allowing for the secretion of IL‐1β, a cytokine which is required for the polarization of IFN‐γ‐producing CD8+ T cells." (PMID 33179413, 2020). "In this same line, inflammatory factors in the tumor microenvironment, including TGF-β, IL-6, IL-1β, IL-8, and others can induce EMT." (PMID 32545405, 2020). "ZER was shown to have an anti-inflammatory effect on the IL-1β signaling pathway by inhibiting the downstream expression of IL-8 and MMP-3, which play a pivotal role in invasion and migration of tumor cells." (PMID 33014808, 2020). "Several other pro-inflammatory targets leading to potentially tumor-toxic effects, such as CCL17, IFNγ, IL1β, and IL6, were increased in tendency." (PMID 32316245, 2020). "IL-1β, while promoting increased synthesis of IL-2, IL-6, and TNF-α, also acts as a tumor growth promoting molecule in conditions of chronic inflammation." (PMID 33718121, 2020). "For example, chemokines (e.g., TNF-α, IL-6, and IL-1b) recruit immunosuppressive neutrophils and M2 macrophages to the TME, thereby inhibiting anti-tumor cell activity (e.g., TCD 8+ lymphocytes and NKTs)." (PMID 32208363, 2020).
tumor (continued). "In 4T1 tumor tissue, ILC3 is a major cellular source of IL-22 which can be increased by giving IL-1β and IL-23." (PMID 32649314, 2020). "Finally, in the lung, commensal bacteria stimulate Myd88-dependent IL-1β and IL-23 production from resident macrophages, inducing proliferation and activation of γδ T-cells that produce effector molecules (e.g., IL-17) to promote inflammation and tumor cell proliferation." (PMID 32635472, 2020). "Tumor supporting cytokines are released from tumor and stromal cells upon AT1 receptor activation via Ang II including, TGF-β and Interleukins (IL-1α, IL-1β, IL-6, IL-8)." (PMID 32503281, 2020). "In our previous study, we determined that ATP treatment-induced activation of the inflammasome increased the secretion of IL-1β in a P2Y2R-dependent manner, ultimately resulting in increased tumor invasion and progression." (PMID 32397236, 2020). "It was also reported that ATLIII inhibits mast cell proliferation, upregulates anti-inflammatory cytokines, and inhibits pro-inflammatory cytokines such as IL-6, IL-8, IL-1β, and TNF-α in tumor microenvironment." (PMID 32038231, 2019). "In the present study, we report that tumor-derived IL-1α and IL-1β exert a primary role in driving TSLP secretion by CAF and that in vivo treatment with anakinra significantly reduces TSLP expression in the tumor." (PMID 30760333, 2019). "Simultaneously, IL-1β induces MMP-9, which has a role in local extracellular matrix degradation and tumor invasion." (PMID 30642137, 2019). "Of these molecules, IL-1β, IL-6, TNF-α, and IL-4 promote the phosphorylation of downstream proteins, e.g., NF-κB and STAT3, which then lead to inflammation, tumor proliferation, and prevention of apoptosis in cancer." (PMID 31781219, 2019). "Here the authors show that replacing TGFβ with IL-1β induces a distinct IL-9+ CD4+ population that have strong cytotoxic and anti-tumor activity in preclinical mouse models." (PMID 30914642, 2019). "M1 macrophages play critical roles in innate host defense and killing tumor cell by producing reactive oxygen/nitrogen species (ROS/RNS) and pro-inflammatory cytokines such as IL-1β, IL-6, tumor necrosis factor α (TNF-α)." (PMID 31629410, 2019). "In tumor tissue in the CC group, ANGPTL-4 showed a significant positive correlation with IL-1β (p < 0.01), a positive correlation with TNF-α (p ≤ 0.05), and a positive correlation with NFκB (p < 0.05)." (PMID 31741709, 2019). "When used in combination with ACT, IL-1β enhanced the accumulation and effector function of adoptively transferred tumor-reactive CD8+ T cells at tumors, resulting in improved tumor regression and mouse survival." (PMID 31405895, 2019). "The correlation between tumor OSM and IL-1β expression and metastatic capacity was assessed in the Curtis patient dataset." (PMID 31007849, 2019). "Macrophage accumulation, oxidation of LDL-C, secretion of IL-1β, TNF-α and other inflammatory factors would promote formation of tumor plaques and inflammatory reactions." (PMID 31341840, 2019). "Several studies have demonstrated that IL-1β is able to activate both MMP9 and VEGF, thus stimulating tumor invasiveness and angiogenesis." (PMID 31231208, 2019). "In view of their high relevance to tumor progression in TNBC, TNFα and IL-1β were selected as representatives of the pro-inflammatory TME in our study." (PMID 31031757, 2019). "Molecules involved in MSCs homing to tumor microenvironments are mainly consisting of several inflammatory cytokines (TNF-α, IL-1β, IFN-γ, and IL-6), chemokines (CXCR4, CXCL7, CXCL6, and CXCL5) and growth factors (PDGF, HGF)." (PMID 31827403, 2019). "Tumor-associated macrophages (TAMs), neutrophils and CAFs in the TME are the major cell types that secrete IL-6 and IL-1β and are responsible for the activation of STAT3 in tumor cells." (PMID 30927928, 2019). "For mice treated with CMS, serum levels of ROS and cytokines (IL-6, IL-1β, and COX2) significantly increased; the tumor grew faster in CMS-induced mice." (PMID 31396300, 2019).
tumor (continued). "A synergistic effect of anti-IL-1β and anti-PD-1 treatment with antibodies was capable of altering TME cell populations in favor of an anti-tumor phenotype." (PMID 31231372, 2019). "By specifically targeting the expression of NLRP3 and IL-1β in mammary fibroblasts, we showed in multiple mouse models that CAF-derived inflammasome is functionally important for facilitating tumour growth." (PMID 31558756, 2019). "Inflammatory cytokines produced by the tumor or adipose tissue such as IL-6, TNF-α, and interleukin-1 beta (IL-1β) contribute to lipolysis, fat oxidation, and decreased lipogenesis as well as browning of white adipose tissue (beige adipose tissue)." (PMID 31683709, 2019). "Some studies have shown that low concentrations of IL-1β promote the secretion of IL-17 from CD4+ T cells, inhibiting the body’s anti-tumor mechanisms." (PMID 31754923, 2019). "Diverse cytokines and factors, including VEGF, granulocyte-macrophage colony stimulating factor (GM-CSF), IL-6, IL-10, TGF-β, interferon (IFN)-γ, IL-1β, and CCL2, are main attractors of MDSCs toward tumor tissue and affect their activation." (PMID 31484464, 2019). "The genes that were overexpressed in both senescent thyrocytes and at least one tumor cell line included genes coding for: the chemokines CCL3 and CCL-4, the cytokine IL-1β, the matrix-related protein SPP1, and the enzyme PTGS2." (PMID 31113465, 2019). "In our experimental model, enhanced secretion of IL-1β, PGE2, TNF-α, and IL-6 occurs following CRC cells/LSECs crosstalk in a tumor LFA-1/LSEC ICAM-1 interaction dependent fashion." (PMID 31511625, 2019). "In fact, in our study, pro-inflammatory cytokine production, such as IL1β and IL6, was blocked after 24 h of tumor induction." (PMID 31712726, 2019). "The second wave of increased IL1β, TNFα, and IL6 expression is observed in the 5th day of tumor growth while IL10 second wave occurred two days earlier." (PMID 31712726, 2019). "And the expression of IL‐6, IL‐1β, TNF‐α and MMP9 in tumor samples were also markedly up‐regulated compared with non‐tumor parts." (PMID 30903649, 2019). "The results would provide a novel anti-cancer strategy to modulate tumor microenvironment by suppressing NLRP3 inflammasome and consequently reducing IL-1β production." (PMID 31439870, 2019). "Various tumor originated cytokines, such as G-CSF, GM-CSF, VEGF, MCP-1 and IL-1β, have been demonstrated to induce MDSCs infiltration." (PMID 31500650, 2019). "In a co-culture system, we observed that the effects of human bone marrow-derived MSCs (hBMSCs) on cancer cells were largely dependent on the expression of IL1β and CDH1 by tumor cells." (PMID 30993013, 2019). "Together these data highlighted 5-FU-induced IL-1β secretion downregulation by DHA-treated MDSC and potentiation of 5-FU therapy in DHA-supplemented tumor-bearing mice." (PMID 31217433, 2019). "Additionally, it was observed that in tumour-naïve mice, a single dose of IL-1β dual selective antagonist reduces osteoclast and osteoblast activity and IL-1β expression, also following continuous administration of IL-1β dual selective antagonist for more than 21 days." (PMID 31847214, 2019). "Next, we evaluated the levels of AIM2 in tumor tissues and found that luteolin administration significantly downregulated AIM2, caspase-1, and IL-1β expressions at mRNA levels." (PMID 30833546, 2019). "ATP abundant in tumor microenvironment stimulates the NLRP3 inflammasome in macrophages, releasing mature IL-1β to the tumor microenvironment to enhance the metastatic potential of cancer cells." (PMID 31439870, 2019). "Using the Curtis dataset, a significant increase in tumor OSM expression, as well as tumor IL-1β expression, was seen in ER− samples compared to ER+ samples." (PMID 31007849, 2019). "It was demonstrated that HSP72 and HSP105 expressed on the surface of tumor-derived EVs promoted DCs to produce high levels of pro-inflammatory cytokines (IL-6, PGE2, IL-1β, TNF-α) in a TLR2- and TLR-4–dependent manner." (PMID 31680949, 2019).
tumor (continued). "Despite IL-1β and MCP-1 have reported to be oncogenic, their potential anti-tumor activities cannot be excluded." (PMID 31816951, 2019). "Based on the intersection of interleukin superfamily signature between human BC tissues and cell lines to exclude the tumor heterogeneity, both TNBC tissues and cell lines dominantly expressed IL1A, IL1B, IL8, and IL32." (PMID 30728901, 2019). "These mutant strains can induce tumor cells to secrete antitumor cytokines, such as IL-1β, IL-18, and TNF-α, thereby suppressing the proliferation of tumor models in mice." (PMID 31598148, 2019). "By secreting cytokines such as IL-6, IL-18, TNF-α, TNF-β, IL-1β, IFN-γ and IL-23, arginase 1 (ARG1) and ECM-modifying enzymes into the TME, TAMs contribute to tumor cell growth, angiogenesis, invasion and metastasis." (PMID 30781344, 2019). "In the COS-treated CRC group (CMCOS), COS protected mice from CRC by decreasing the disease activity index, tumor incidences and multiplicity, and the mRNA levels of COX-2, IL-6, TNF-α, IL-1β, IL-10, and IKK-β mRNA in colonic epithelial cells." (PMID 31620100, 2019). "Early production of TNF-α, IL-1β, and IL-6 in the liver after DEN treatment correlated with tumor development in AIRmax mice." (PMID 31049358, 2019). "The pro-inflammatory cytokine, IL-1β, provokes the epithelial–mesenchymal transition (EMT) of tumor cells due to activation of the IL-1β/interleukin 1 receptor type 1 (IL-1RI)/β-catenin signaling pathway and recruits additional immune cells to the tumor site." (PMID 31861801, 2019). "Thus we investigated whether Th9IL-4+IL-1β cells are also tumor killers." (PMID 30914642, 2019). "To further explore this possibility, we created the tumor microenvironment in NSG (NOD-scid IL2Rgammanull) mice using TAFs and the ER+ MCF7 BCCs and examined the impact of blocking IL1β (Anakinra) and PDGF ( SU16f) signaling on tumor growth in vivo." (PMID 31419632, 2019). "Therefore, we analysed whether CAF-derived IL-1β has a role in affecting tumour cell invasiveness." (PMID 31558756, 2019). "qRT–PCR demonstrated that the tumour tissue in the CDDP group showed an increased expression of P21 and SASP genes, such as IL-1β, IL-6 and IL-8." (PMID 29449532, 2018). "The secretion of IL-1β by macrophages is also required to activate Wnt signaling and β-catenin/TCF4 transcriptional activity in tumor cells promoting tumor growth." (PMID 30619282, 2018). "Multiple inflammatory cytokines, including IL-1β, IL-6, and TNF-α, increase proliferation and invasion of tumor cells." (PMID 30298062, 2018). "Some studies also indicated that IL-1β induces upregulation of CXC chemokine receptor 3 (CXCR3) in different types of cells, such as T lymphocytes, natural killer cells, and tumor cells." (PMID 30359318, 2018). "After CM stimulation, the tumor educated macrophages (TEM) decreased the expression of M1 macrophage markers, such as IL-1b, IL-6 and increased the expression of M2 macrophage markers including Arg1 and CD163 compared with M0 macrophage." (PMID 30180849, 2018). "TNF, IL6 and ANGPT2 were expressed equally by both DLD1 and SKBR7 xenografts, whereas higher levels of IL1B, IL4, IL13 and VEGFA were found in DLD1 tumours." (PMID 29367702, 2018). "Overexpression of immunosuppressive cytokines, such as IL-10, TGF-β and IL-1β can cultivate a Tumor Microenvironment (TME) conducive to evasion and tumor proliferation." (PMID 29988281, 2018). "NF-κB signaling in cancer cells can be activated by factors such as IL-1β, TNFα and IL-8, IL-6 and MCP-1 secreted by cells in the microenvironment of the tumor, e.g. macrophages or adipocytes." (PMID 29930291, 2018). "Two additional genes (CD14 and CSNK2A1) were dysregulated in MSS tumours and two genes (CARD11 and VCAM1) were downregulated and six genes were upregulated (LYN, TICAM2, ICAM1, IL1B, CCL4 and PTGS2) in MSI tumours." (PMID 29188362, 2018).